SMAD1 (SMAD family member 1)
Diseases named in the same sentence as SMAD1 in open-access papers (continued):
Sharing a sentence is not in itself a finding about the gene and the disease.
tumor (103 papers, 2009 to 2026). "Our findings are consistent with studies on solid tumors in which upregulation of SMAD1 has been associated with tumor aggressiveness and poor outcomes." (PMID 34134766, 2021). "Further analysis of proteomic data revealed that the AGI was strongly correlated with the expression of cell-cycle-related proteins, including pChk1, pChk2, and CyclinB1, and other tumor hallmark proteins, such as eIF4G, pPI3K, Src, Smad1, and Smad3." (PMID 34094917, 2021). "Recently, a report showed BMP-6 stimulates tumor-associated macrophages to produce IL-1α through a crosstalk between Smad1 and NF-kB1." (PMID 28068414, 2017). "Indeed, Smad1 is identified as a dominant downstream effector of Uev1A, which unravels the mechanism underlying Uev1A-orchestrated tumor suppression in OS." (PMID 28771228, 2017). "Tumor BC_2L harbored a mutation in SMAD1, a gene regulating cell survival." (PMID 27383411, 2016). "To further explore this, we analyzed the expression of ACVRL-1, the phosphorylation levels of Smad1/5/9, and the expression of ID-1 in tumor tissues." (PMID 41579221, 2026). "The expression level of Smad1 in these cells was positively correlated with tumor volume derived from the 3D‐cultures, indicating that higher Smad1 corresponds to stronger tumorigenicity." (PMID 39629919, 2025). "Low dose TMZ resulted in a gradually decreased tumor volume among the two groups, and Smad1 KO induced a significantly smaller tumor at the final timepoint." (PMID 39629919, 2025). "Correlation analysis indicated that Smad1 protein levels were positively correlated with the amplification of the patient‐derived tumor spheres." (PMID 39629919, 2025). "On the contrary, in naïve GBM cells, K373R introduction demonstrated its promotion in tumor growth and its anti‐apoptotic effect as wild‐type Smad1 done." (PMID 39629919, 2025). "Consistent with the results of the intracranial xenograft, tumor weight analysis of derived tumors on the 21st day after implantation showed that Smad1 depletion significantly inhibited the growth of subcutaneous transplanted tumors." (PMID 39629919, 2025). "Smad1 knockout resulted in significant tumor regression, confirming the effect of Smad1 KO on chemosensitivity promotion." (PMID 39629919, 2025). "CD109 is highly expressed in osteosarcoma, promote tumor cell migration via suppression of bone morphogenetic protein-2 (BMP-2)-induced Smad1/5/9 phosphorylation, where its expression correlates with poor prognosis." (PMID 39990858, 2024). "The MEK/ERK/SMAD1 signaling pathway emerges as a critical player in the complicated landscape of cancer biology, exerting profound influences on tumorigenesis, tumor growth, invasion, and metastasis." (PMID 38785990, 2024). "CD109 overexpression correlates with poor prognosis and promotes tumor cell migration via suppression of BMP-2-induced Smad1/5/9 phosphorylation." (PMID 39990858, 2024). "We utilised adenoviruses to efficiently transduce tumour cells with the specific Smad1/5 inhibitor Smad6 (Ad-Smad6-M2 adenovirus) or the Smad1/5 and Smad2/3 inhibitor Smad7 (Ad-Smad7-M2 adenovirus)." (PMID 39724753, 2024). "Compared with the matched adjacent tissues, the phosphorylation level of Smad1/5/9 in tumor biopsy tissues was higher in patients with the locally-advanced disease (Patient No. 12)." (PMID 36756161, 2023). "Our results suggest that TrkB suppresses BMP-mediated tumor inhibition by regulating the processes upstream of SMAD1." (PMID 32731498, 2020).
tumor (continued). "Suppression of SMAD1/5/8 phosphorylation by RK783 treatment in vivo was confirmed by immunofluorescent staining of tumor sections." (PMID 33298901, 2020). "Treatment at these concentrations also lead to a substantial reduction in pharmacodynamic biomarkers in HSJD-DIPG-007 xenograft tumours, showing a near-ablation of phospho-SMAD1/5/8 and ID1 with LDN-193189, and to a lesser extent with LDN-214117." (PMID 31098401, 2019). "Activation of the pathway, as evidenced by immunofluorescence staining against phosphorylated SMAD1/5/9 was widely present in tumour cells, particularly in proximity to the clusters, but was absent from the palisading epithelium." (PMID 29541918, 2018). "For example, Smad1 can be induced by many tumor-stimulating cytokines such as the bone morphogenetic protein 2 (BMP2) and TNFα and plays important roles in cell invasion and metastasis." (PMID 29299158, 2017). "Collectively, we concluded that Uev1A is a cofactor of the E2-E3 complex UecH5B-Smurf1 that promotes Smad1 ubiquitination and subsequent degradation, leading to OS differentiation and inhibition of tumor growth." (PMID 28771228, 2017). "For example, only 54 pairs of clinical samples and one human PC cell line PC 3 were used to detect the influence of miR-199a-3p targeting Smad1 on tumor proliferation, migration and invasion." (PMID 28881744, 2017). "Consistent with previous observations, the expression of Smad1 was significantly higher in tumor compared with the para-tumor samples." (PMID 29299158, 2017). "In HCC, the inhibition of the BMP-4/SMAD1 signaling has been reported to suppress tumor migration, invasion, and EMT." (PMID 27661009, 2016). "The knockout of SMAD1 and SMAD5 in somatic cells of male and female gonads promotes metastatic granulosa cell tumorigenesis in mice, which implicated SMAD1 and SMAD5 as critical tumor suppressors." (PMID 27661009, 2016). "Accumulating evidence also indicates that TGF-β can engage and activate Smad1/5/8 during tumor progression." (PMID 27626309, 2016). "We analyzed total LKB1 protein levels and phospho-Smad1/5/8 as a read-out of BMP signaling in the tumor tissue, while a Smad1 antibody served as control." (PMID 26701726, 2016). "Our data clearly indicate that miR-26b-5p directly represses invasion and tumor metastasis by inhibiting SMAD1." (PMID 27027434, 2016). "We showed a synergistic role for TGFβ and notch pathways in this phenotypic change, as simultaneous inhibition of notch and TGFβ down-regulated Smad1/5 phosphorylation and Jag1KD tumor cells were unable to initiate the process." (PMID 25623554, 2015). "We showed that the tumor-stimulated processes leading to creation of ECMes are also mediated by phosphorylation of TGFβ/Smad1/5 in synergy with notch pathway activation." (PMID 25623554, 2015). "Our data confirmed that tumor-activated TGFβ/Smad1/5 phosphorylation was regulated by synergistic activation of notch and TGFβ pathway by showing that TGFβ and Jag1 were capable of inducing Smad5 phosphorylation as well as Hes1 up-regulation." (PMID 25623554, 2015). "Coupled with the changes in tumor sizes, Smad1/5/8 phosphorylation induced by Dragon in tumor tissues at day 22 was inhibited by anti-BMP2/4 antibody." (PMID 26029998, 2015). "Consistent with the results from cultured cells, Smad1/5/8 and Erk1/2 phosphorylation was down-regulated in the Dragon knockdown tumor tissues collected at day 31 after the injection, while AKT and p38 phosphorylation was not altered." (PMID 26029998, 2015). "The attenuated expression of endoglin and TGF-β together further induce inhibition of cascade activation of ALK1 (Smad1/5/8) in endothelial cells, resulting in decreased tumor angiogenesis and suppression of tumor growth." (PMID 23209720, 2012). "Downregulation of TGF-β signalling (SMAD1) is reported in tumour tissues of familial oesophageal SCC patients." (PMID 21326238, 2011).
tumor (continued). "Smad1 depletion resulted in a significant decrease in tumor growth and tumor cell proliferation." (PMID 39629919, 2025). "Besides, high levels of CHRDL1 inhibited BMP4-induced Smad1/5/8 phosphorylation, thereby suppressing tumor growth." (PMID 40837015, 2025). "Consistently, BMP4 induces SMAD1/5/8 phosphorylation, which profoundly inhibits tumor growth." (PMID 36175474, 2022). "Interestingly, the level of phosphorylated Smad1/5 is elevated in the tumor tissues of patients with cetuximab-resistant oral squamous cell carcinoma with poor prognosis." (PMID 35693928, 2022). "In our study, we found that SMAD1 functioned as a tumor promoter, which may have partially contributed to the progression of BCR." (PMID 34136527, 2021). "In addition, the knockdown of TrkB restored the tumor-inhibitory effect of BMP-2 via the activation of SMAD1." (PMID 32731498, 2020). "One study suggested that FAM83H-AS1 might inhibit TGF-β signaling pathway by downregulating SMAD1/5/9, preventing the anti-tumor effect of TGF-β signaling." (PMID 32165862, 2020). "Moreover, BMP4 function as tumor suppressor in in-vitro and orthotopic models of glioblastoma multiforme, where it limits tumor cell migration and invasion via SMAD1/5/8 mediated enhancement of E-cadherin and claudin expression." (PMID 31547567, 2019). "The tumor-suppressing effect of RGMB was exerted through inhibition of the Smad1/5/8 pathway." (PMID 26910889, 2016). "In addition, tumour-epithelial p-Smad1/5 staining was consistently more abundant in tumours from Ptch1ΔCol1 mice, indicating increased epithelial BMP downstream activity as a result of the augmented stromal Hh signal." (PMID 27492255, 2016). "Among them, SMAD1 was chosen for further experimental validation, not only because it was identified as a target of miR-26b-5p by all three databases, but also due to its well-known importance in both tumor metastasis and EMT." (PMID 27027434, 2016). "However, BMP2 has been shown in some settings to enhance tumor growth in vivo due to activation of Smad-1/5." (PMID 22870311, 2012). "In addition to activation of the ID1 pathway, a crosstalk between SMAD1 and NF-κB1 acting as a tumor inducer circuit, may provide a novel mechanism for SMAD1-mediated myelomagenesis." (PMID 34134766, 2021). "Furthermore, BMP4 was capable of inducing tumor dormancy via activating SMAD1/5 signaling and BMP7 can inhibit tumor cell growth and drive CSCs into dormancy by mediating the expression of N-myc downstream-regulated gene 1 and activating p38 MAPK and p21 signaling pathways." (PMID 34712663, 2021). "Moreover, the expression of both miR-144 and SMAD1 was determined in xenograft tumour samples." (PMID 29260980, 2018). "When compared to the normal human astrocytes (NHAs) and hNSCs, hNSCs-BMP4 could significantly inhibit the invasive growth of hGSCs, promote their differentiation and apoptosis by activating Smad1/5/8 signaling, and prolong the survival time of the tumor-bearing nude mice." (PMID 26908439, 2016). "Specifically, the upregulation of SMAD1, SMAD3, SMAD4, BMP2, MAPK1, and SKIL—driven by promoter hypomethylation and reduced expression of tumor-suppressive microRNAs—leads to enhanced activation of both canonical and non-canonical branches of TGF-β signaling." (PMID 40869118, 2025). "Considering the different sizes of Smad1 NC and KO tumors before TMZ treatment, the inhibitory rate was calculated by dividing the tumor volume during treatment by the tumor volume before treatment to compare chemosensitivity." (PMID 39629919, 2025).
tumor (continued). "TAM M2 can activate Smad2/3 and Smad1/5/8, thereby promoting the epithelial–mesenchymal transition (EMT) and tumor metastasis." (PMID 40299539, 2025). "SMAD1, in the context of TGF-β signaling, contributes to angiogenesis regulation, further highlighting the convergence of these pathways in shaping the tumor microenvironment." (PMID 38785990, 2024). "In tumor tissues, we found that CRC patients with positive VPS9D1-AS1 expression shown higher levels of TGF-β, TGFBR1, and SMAD1/5/9." (PMID 36458816, 2022). "Mechanistically, tumor cell-derived BMP-7 downregulates MAP kinase (MAPK) 14, which regulates some cytokines and chemokines, including IL1A, IL1B, TNF, and CCL5 via Smad1 activation in macrophages." (PMID 35693928, 2022). "The phosphorylation of Smad1/5/8/ and activation of ID1 contributed to angiogenesis and tumor growth in lung cancer." (PMID 32547321, 2020). "In light of our current data it will be important to investigate in what tumor contexts ID1 is required for EMT, and more broadly how the TGF-β–SMAD1/5 pathway contributes to different aspects of tumorigenesis." (PMID 29376829, 2018). "Several reports using genetically modified mouse models highlight the importance of TGFB superfamily signaling components, such as INHA, SMAD3, SMAD1/5, and BMPR1A/BMPR1B, in sex cord-stromal tumor development." (PMID 29221447, 2017). "To examine the protein level of Ajuba and Smad1 in CRC specimens, we performed immunohistological chemistry (IHC) assays on tumour tissues." (PMID 29299158, 2017). "All together, our data imply that BMP4/Smad1 signaling can be inhibited through SMAD1 repression by miR-26b-5p, thus suppressing EMT, tumor invasion and metastasis." (PMID 27027434, 2016). "Over-expression of miR-26b-5p inactivated the bone morphogenetic protein 4 (BMP4)/Smad1 pathway by upregulating SMAD1 in HCC cells and suppressing EMT, tumor migration and invasion." (PMID 27027434, 2016). "During early tumor development, BMP signaling may promote epithelial-mesenchymal transition (EMT) through SMAD1/5/9 phosphorylation, while in advanced stages, it may potentially suppress excessive proliferation of metastatic foci." (PMID 40837015, 2025). "A significant alteration of SMAD1 was identified across all tumor samples and paired with normal tissues." (PMID 39629919, 2025). "Since in tumor cells the stimulated TGFb receptor phosphorylates SMAD1/5 and promotes cell migration, it is concluded that the TGFb-TGFBR1-SMAD1/5 axis could be of clinical interest." (PMID 39364009, 2024). "SMAD1 was correlated with patient prognosis, and SMAD2 was correlated with tumor stage." (PMID 36969909, 2023). "Further, AID−/−/Eμ-TCL1 CLL cells downregulate the tumor suppressive SMAD1/S1PR2 pathway and have altered homing to non-lymphoid organs." (PMID 36042317, 2022). "Reduced SMAD1 and SMAD4 expression was seen across all cancer subtypes, but SMAD5 was differentially expressed: it was downregulated in canonical tumours (n = 149), but was retained and modestly upregulated in poor‐prognosis, mesenchymal tumours (n = 78)." (PMID 28299802, 2017). "Studies suggest that SMAD1, a downstream effector in the TGF-β pathway, may interact with MEK/ERK signaling to fine-tune cell proliferation in specific cancer contexts, adding an additional layer of complexity to the regulation of tumor growth." (PMID 38785990, 2024). "The importance of ALK1 and SMAD1/5 for endothelial/vascular function is demonstrated by the observations, that genetic elimination of either ALK1 or SMAD5 is embryonic lethal due to cardiovascular defects and that ablation of ALK1 decreased tumor angiogenesis in adult mice." (PMID 22761782, 2012).
tumor (continued). "Smad1 but not Smad2/3 protein levels were significantly decreased, suggesting that endoglin plays a role in the attenuation of endothelial tumor growth and tumor angiogenesis." (PMID 23209720, 2012). "Consistently, the transcriptional corepressor c-Ski, which is highly expressed in ccRCC, promotes tumor growth by counteracting the TGFβ-dependent SMAD arm (that requires SMAD2/3), but probably not that related to BMP (that requires SMAD1/5/8)." (PMID 31547567, 2019). "Toxicarioside A altered Smad1 signaling but not Smad2/3 signaling only in HUVECs, not in CT24 or LL/2 tumor cells." (PMID 23209720, 2012). "No previous literature has highlighted a role for SMAD1 in HNSCC but the decreased expression of both this and TGFβR2 could indicate a reduced proliferative capacity of the tumour on the device." (PMID 37760543, 2023).